PRMT1 (protein arginine methyltransferase 1)
Diseases named in the same sentence as PRMT1 in open-access papers (continued):
Sharing a sentence is not in itself a finding about the gene and the disease.
tumor (continued). "Further analysis revealed the tumor-suppressive function of PRMT1 after its knockdown in vivo and in vitro." (PMID 40858547, 2025). "Collectively, these results further reinforce the necessity of the oligomeric state for PRMT1’s functionality in PDAC and confirm that the disruption of PRMT1 oligomerization suppresses tumor growth by influencing RNA metabolism." (PMID 40675804, 2025). "Although the PRMT1 knockdown group alone showed good anticancer effects, the inhibited tumor growth was restored after the combined inhibition of STING." (PMID 40858547, 2025). "PRMT1 facilitates tumor growth by enriching the H4R3me2a mark at the promoters of proproliferative genes to enhance their transcription." (PMID 41256732, 2025). "In summary, PRMT1 is a master regulator of oncogenesis, driving tumor initiation and progression through the precise epigenetic control of fundamental cellular processes such as gene transcription, cell cycle progression, apoptosis, EMT, and angiogenesis." (PMID 41256732, 2025). "The tumor immunophenotype analysis indicates that elevated PRMT1 levels hinder immune cell infiltration in tumors." (PMID 40927753, 2025). "Together, these data indicate that PRMT1 promoted HCC tumor growth through YAP methylation in vitro and in vivo." (PMID 39367565, 2024). "Firstly, PRMT1 exhibits different roles in different stages of tumor development, as demonstrated in alcohol-induced liver cancer." (PMID 38326807, 2024). "By regulating mitochondrial Ca2+ uptake, PRMT1 plays a crucial role in sustaining the vitality and proliferation of tumor cells." (PMID 38326807, 2024). "We and others have revealed that the protein level of PRMT1 is frequently upregulated in HCC to promote tumor growth." (PMID 38839752, 2024). "This review aims to comprehensively examine recent research progress on PRMT1 in tumors, summarizing its potential applications in tumor treatment." (PMID 38326807, 2024). "The clinical connection between the tumor and surrounding normal tissues of 73 HCC patients revealed that PRMT1 was strongly expressed in HCC and strongly linked with both ME2 methylation and poor clinical prognosis, which is consistent with our results." (PMID 39528487, 2024). "The PP2A activator DT-061 inhibits tumor progression through various mechanisms, suggesting its potential to inhibit PRMT1 as part of its tumor-suppressing actions." (PMID 40018367, 2024). "In cellular experiments, PRMT1 also upregulated H4R3me2a to induce tumor cell proliferation and promote tumor cell metastasis via the tumor necrosis factor signaling pathway." (PMID 39619442, 2024). "In the subsequent section, we present a comprehensive review of research findings on PRMT1 in tumors, exploring its potential value in tumor therapy." (PMID 38326807, 2024). "PRMT1 expression level in PDAC is found to be positively correlated with the tumor size and post-operative patient prognosis." (PMID 38612768, 2024). "Recent research revealed that PRMT1 can inhibit the enzymatic activity of cGAS in part through PRMT1-mediated Arg methylation, thereby suppressing the anti-tumor immune response of cells." (PMID 40018367, 2024). "Several studies have found that overexpression of PRMT1, PRMT3, and PRMT6 is associated with increased progression and invasiveness of many tumor types." (PMID 38663941, 2024). "Studies have shown that PRMT1-mediated methylation is an important biomarker and potential target in tumor therapy." (PMID 39741976, 2024). "Numerous studies have revealed that PRMT1 exhibits oncogene-like properties, playing a crucial role in regulating tumor cell proliferation, metastasis, and drug resistance." (PMID 38326807, 2024). "Immunohistochemical staining of sections from tumor xenograft models demonstrated reduced protein levels of PRMT1 and c-MYC in tumor xenografts derived from TRIM25-knockdown GBM#021 cells relative to controls." (PMID 38303029, 2024).
tumor (continued). "The transcriptional activity of YAP and TEAD were further characterized by real‐time qPCR and immunofluorescence assay, and a subcutaneous and orthotopic tumor mouse model was used to assess the effect of PRMT1‐knockdown on HCC tumor growth." (PMID 39367565, 2024). "In summary, while PRMT1 has demonstrated a significant impact on tumor development, a comprehensive understanding of its role and potential therapeutic applications remains a work in progress." (PMID 38326807, 2024). "This review suggests that targeting the PRMT1-cGAS-STING pathway with immune checkpoint inhibitors is likely a promising approach in tumor immunotherapy." (PMID 40018367, 2024). "Secondly, PRMT1 exhibits different mechanisms of action in regulating the same signaling pathway in different types of tumor cells." (PMID 38326807, 2024). "Because PRMT1 promotes HCC growth, the E3 ligase, which downregulates PRMT1, theoretically plays a tumor-suppressive role in HCC." (PMID 38839752, 2024). "In conclusion, PRMT1, as a novel effector, plays a crucial role in promoting the stem cell characteristics of esophageal cancer while also maintaining tumor cell proliferation and migration." (PMID 38326807, 2024). "It is well-established that PRMT1 plays a crucial role in regulating gene transcription, protein expression, and tumor cell differentiation, which contribute to the proliferative and metastatic behaviors exhibited by tumors." (PMID 38326807, 2024). "In this review, we present an overview of recent advancements in PRMT1 research across different tumor types, with a specific focus on its contributions to tumor cell proliferation, metastasis, invasion, and drug resistance." (PMID 38326807, 2024). "PRMT1, one of the most crucial PRMTs, plays a critical role in tumor progression and innate immunity." (PMID 40018367, 2024). "Silencing PRMT1 in HCC cells inhibited cell proliferation and tumor growth, while PRMT1‐overexpression promoted HCC growth through YAP methylation." (PMID 39367565, 2024). "It was found that KD of PRMT1 suppressed the growth of tumor xenografts from mice fed with a +SG diet, as evidenced by decreased tumor size, volume, and weight." (PMID 38839752, 2024). "Our experiments utilizing different MM cell lines consistently showed that knockout of PRMT1 significantly delayed MM tumor progression in vivo and extended the survival of tumor-bearing mice." (PMID 37600810, 2023). "Here we revealed a critical role of PRMT1 in directly methylating cGAS and blocking cGAS/STING DNA sensing signaling, thus promoting tumor immune evasion, which provides a rationale for PRMT1 as a promising immunotherapeutic target." (PMID 37193698, 2023). "As such, PRMT1 inhibition elevates tumor-infiltrating lymphocytes in a cGAS-dependent manner, and promotes tumoral PD-L1 expression." (PMID 37193698, 2023). "Our study not only demonstrates a PRMT1-RIP3 axis in regulating necroptosis and tumor immune microenvironment but also reveals PRMT1 and RIP3 methylation as the molecular prognosis biomarkers of colon cancer." (PMID 37005412, 2023). "As the cellular effects of Prmt1 are in part regulated by hnRNP F, we determined the relative contributions of these two proteins to tumor cell proliferation." (PMID 37673892, 2023). "Given the effect of PRMT1 in preventing differentiation of activated B cells and since differentiation is a tumor suppressor phenomenon, we asked if PRMT1 played a similar role in BCL cells." (PMID 37310381, 2023). "Meanwhile, the combination of BTZ and sg-PRMT1 resulted in significant tumor inhibition in a xenograft MM mouse model." (PMID 37558663, 2023). "Potential anti-tumor effects of a protein arginine n-methyltransferase type I (PRMT1) inhibitor were elicited in 2D and 3D cell culture experiments using cell viability and apoptosis assays." (PMID 36710341, 2023). "The results showed that PRMT1 knockout significantly restrained tumor volume and reduced tumor weight." (PMID 37558663, 2023).
tumor (continued). "circTBC1D14 suppressed the ubiquitination of PRMT1 protein, thereby increasing the tumor aggressiveness of TNBC." (PMID 36806670, 2023). "Using xenograft models, we found that targeting PRMT1 genetically or pharmaceutically attenuates the MM tumor growth and mitigates the tumor burdens in vivo." (PMID 37600810, 2023). "Here the authors show PRMT1 suppresses the anti-tumor immune response via arginine methylation of cGAS." (PMID 37193698, 2023). "In vivo studies using a xenograft model revealed that targeting PRMT1 by either CRISPR/Cas9-mediated knockout or MS023 treatment significantly attenuated MM tumor growth and prolonged the survival of tumor-bearing mice." (PMID 37600810, 2023). "Hematoxylin-eosin (H-E) staining of tumor tissues showed an increase in necrotic areas in the PRMT1 knockout group." (PMID 37558663, 2023). "Mechanistically, we demonstrate that Prmt1 affects tumor growth primarily by regulating de novo protein translation though Ubap2l’s control of rRNA and ribosomal proteins." (PMID 37673892, 2023). "Specifically, in TNBC, our studies show that genetic and pharmacological inhibition of PRMT1, the main target among type I PRMTs, induces cell cycle arrest and apoptosis, leading to tumor suppression in a subset of TNBC." (PMID 35578032, 2022). "Taken together, these studies suggested that effective inhibition of PRMT1 can control T cell-mediated tumor killing and can effectively remodel the tumor immune microenvironment." (PMID 36713412, 2022). "Collectively, our data suggest that PRMT1-mediated HBP1 methylation facilitates PRMT1-induced metastasis in tumor cells." (PMID 35941115, 2022). "PP2A has been reported to negatively regulate PRMT1 through dephosphorylation at S297, supporting a possible tumor suppressive role for PP2A in the context of PRMT1 regulation." (PMID 35118387, 2022). "PRMT1-mediated methylation of HBP1 alleviates the repressive effects of HBP1 on tumor metastasis and growth." (PMID 35941115, 2022). "Accordingly, G98R overexpression inhibited tumor cell metastasis and growth compared with PRMT1 overexpression." (PMID 35941115, 2022). "More importantly, scCRISPR screen platforms enable us to determine the heterogeneous changes of gene expression in Prmt1, Ripk1 or Axl knockout (KO) tumor cells in the presence of immune attack, which cannot be easily assessed by bulk RNA-seq." (PMID 36518525, 2022). "Activation of Notch/Wnt signaling by PRMT1 in tumor initiating cells was responsible for chemoresistance phenotype." (PMID 33968932, 2021). "PRMTi also led to robust suppression of in vitro cell growth comparable to genetic protein depletion in multiple PDAC models, suggesting that PRMT1 catalytic activity is required for tumor cell growth." (PMID 34330913, 2021). "In CRC, methylation of R198/200 in the extracellular domain of EGFR by PRMT1 enhanced receptor dimerization and cell proliferation, resulting in tumor cell resistance to the anti-EGFR monoclonal antibody cetuximab." (PMID 33420374, 2021). "Depletion of PRMT1 in tumors was confirmed by immunohistochemistry and Western blot analysis of tumor lysates (respectively)." (PMID 34330913, 2021). "Assuming that a tumour spheroid formation assay is an important approach for enriching TICs, we examined the impact of PRMT1 on tumour self-renewal ability." (PMID 31043582, 2019). "To begin, the ONCOMINE and CCLE data showed that the expression level of PRMT1 was elevated in tumour patients and cell lines of ESCC." (PMID 31043582, 2019). "mRNA PRMT1 expression level in tumor tissue was significantly lower than that in renal parenchyma (p = 0.009)." (PMID 31655611, 2019). "In tumor tissue, mRNA PRMT1 expression level was significantly lower in ccRCC, when compared to pRCC and chRCC (p < 0.001)." (PMID 31655611, 2019).
tumor (continued). "PRMT1 expression was observed in all analyzed tumor types, notably in the majority of ccRCC and pRCC, almost all RO, all MLCRN-LMP, and in minority of chRCC." (PMID 31655611, 2019). "To further demonstrate the effect of PRMT1 mediating tumour stem cell-like properties, we utilized a lentiviral-based knockdown approach to silence PRMT1 expression in ECA109 and TE1 cell line." (PMID 31043582, 2019). "Mounting evidence suggested that PRMT1 is essential to embryonic development and tumor pathogenesis, but its role in normal adult hematopoiesis is less studied." (PMID 31853216, 2019). "As clinical behavior of tumor stage pT1 is similar to pT2, and pT3 to pT4, we analyzed the significance of PRMT1, RUNX1, ZEB1 and TWIST 1 expression in pT1/pT2 versus pT3/pT4 stage group." (PMID 31655611, 2019). "A decrease of relative PRMT1 mRNA expression level was detected in tumor tissue compared to adjacent renal parenchyma." (PMID 31655611, 2019). "In both cohorts, mRNA PRMT1 expression level was downregulated in tumor tissue, when compared to counterparts, while the lowest level was observed in ccRCC type." (PMID 31655611, 2019). "PRMT1 expression in tumor tissue was compared to the IHC expression of EMT-related transcription factors (ZEB1, RUNX1, and TWIST1) and cell surface markers (ß-catenin, N- and E-cadherin)." (PMID 31655611, 2019). "Considering that PAI-1 is critical in tumor migration and invasion, we examined the migration activity of the stable PRMT1-KD SK-N-SH cells." (PMID 30741995, 2019). "We found PRMT1 to be expressed at a 2.02× greater level in EAC tumor cells compared to normal esophageal epithelial cells (P < 0.0001)." (PMID 29868478, 2018). "Analysis of The Cancer Genome Atlas (TCGA) database revealed an increase in UCP2 as well as in PRMT1 mRNA expression in several tumor tissues in comparison to adjacent normal tissue." (PMID 29113301, 2017). "Although any clinical study has not been started yet, small chemical compounds targeting protein arginine methyltransferases including PRMT1 have been developed as anti-tumor agents." (PMID 26460953, 2015). "Future studies could address this by employing combination strategies, such as co‐administration of PRMT1 inhibitors with anti‐angiogenic agents (e.g., bevacizumab), to induce tumor hypoxia and validate the axis in physiologically relevant contexts." (PMID 40884268, 2025). "Moreover, circ-PRMT1 retained its prognostic significance for OS (HR = 3.69; p < 0.001), along with other clinicopathological features of the tumor." (PMID 40724932, 2025). "This suggests that PRMT1 may regulate IL-1β expression, thereby promoting tumor stemness and immune suppression in TNBC, which in turn sustains chemoresistance." (PMID 40927753, 2025). "Additionally, we conducted an in vitro coculture experiment to examine the effect PRMT1 expression levels in GC cells on the polarization of tumor-infiltrating macrophages." (PMID 40858547, 2025). "Since results above showed that PRMT1 was upregulated in human GC tissues and affected cell proliferation, we decided to investigate whether PRMT1 knockdown could inhibit tumor growth in vivo." (PMID 40858547, 2025). "Indeed, they reported that PRMT1 methylated histone H4R3 in tumor-initiating cells (TICs), which modified the genome and caused transcriptional activation of downstream genes." (PMID 40001488, 2025). "The subcutaneous tumor tissue size and tumor weight significantly decreased after PRMT1 knockdown." (PMID 40858547, 2025). "By sensitizing tumor cells to chemotherapy, PRMT1 inhibitors could enhance the effectiveness of current treatments, improving patient outcomes and prolonging survival." (PMID 40927753, 2025). "PRMT1 is also involved in tumor immunity by decreasing the activity and number of CD8+ T cells." (PMID 40001488, 2025). "circ-PRMT1 exhibits distinct molecular features that may independently influence tumor development and progression." (PMID 40724932, 2025).
tumor (continued). "PRMT1 expression also plays a substantial role in tumor immunity." (PMID 40001488, 2025). "These consistent findings suggest that the expression of PBX2, PRMT1, SMARCC1, and IGF2BP2 in tumor tissues could serve as reliable diagnostic markers for HNSCC due to their high sensitivity and specificity." (PMID 40270464, 2025). "Collectively, these findings underscore the importance of PRMTs in shaping anti-tumor immunity and suggest that co-targeting PRMTs, especially PRMT1, may offer a promising approach to improve the efficacy of immune checkpoint therapies." (PMID 41204384, 2025). "Based on these findings, we hypothesize that TRIM21 may act as a tumor suppressor in CRC by negatively regulating PRMT1." (PMID 39890802, 2025). "PRMT1 may play a key role in tumor escape from immune detection, and its inhibition could reactivate the immune system against the tumor." (PMID 40927753, 2025). "To verify whether TRIM21 acts its tumor suppressor function via PRMT1, we overexpressed PRMT1 in CRC cells with a base of TRIM21 overexpression." (PMID 39890802, 2025). "Moreover, investigations of clinical samples have revealed a robust relationship between the expression levels of TK1 and PRMT1 and tumor volume, microvascular invasion, and tumor stage in patients with HCC." (PMID 41256732, 2025). "To determine whether PRMT1 induces the polarization of tumor-infiltrating macrophages by regulating the cGAS/STING signaling pathway in GC cells, we cocultured GC cells and macrophages in vitro." (PMID 40858547, 2025). "Ultimately, we investigated whether the oligomeric state of PRMT1 is required for maintaining PDAC tumor growth in vivo." (PMID 40675804, 2025). "The data above prompted us to explore whether PRMT1 depletion enhances CBP's anti‐tumor efficacy in vivo." (PMID 40270464, 2025). "Since PRMT1 promotes tumor growth beyond its methyltransferase activity, conventional enzymatic inhibitors may have limited efficacy." (PMID 40270464, 2025). "Additionally, we analyzed the correlation between PRMT1 expression and tumor-related immune cells via the TIMER website." (PMID 40858547, 2025). "In these malignancies, PRMT1 functions as a pivotal oncogene by several methods, such as facilitating cell proliferation, suppressing apoptosis, augmenting cell motility and invasion, and influencing the tumor microenvironment." (PMID 41256732, 2025). "Notably, the suppression of tumor growth by PRMT1 KD was aggravated when mice were fed with a -SG diet." (PMID 38839752, 2024). "The stimulatory and inhibitory effects of PRMT1 on growth may vary in different situations, while its ability to inhibit tumor growth depends on the stage of tumor development." (PMID 38326807, 2024). "We next explored the role of PRMT1 on HCC tumor growth via YAP methylation." (PMID 39367565, 2024). "Moreover, furamidine treatment and PRMT1 knockdown potently inhibited the in vivo tumor growth of U87MG GSCs in a CAM model." (PMID 38474197, 2024). "Moreover, we generated a PRMT1‐knockdown Hepa1‐6‐luciferase mouse cell line and examined the effect of PRMT1 in an orthotopic tumor mouse model." (PMID 39367565, 2024). "Therefore, pharmacological inhibition of PRMT1 is an effective strategy to activate cGAS and enhance anti-tumor immunity." (PMID 40018367, 2024). "In addition, the PRMT1 knockdown group (tumor weight of 0.2 mg) showed markedly inhibited in vivo tumor growth of U87MG GSCs compared with the negative control group (tumor weight of 3.7 mg) in the CAM model." (PMID 38474197, 2024). "Consequently, combining PRMT1 inhibitors with anti-PD-1 antibodies in vivo enhanced anti-tumor therapeutic efficacy." (PMID 40018367, 2024).